INS (insulin)
Diseases named in the same sentence as INS in open-access papers (continued):
Sharing a sentence is not in itself a finding about the gene and the disease.
diabetes (continued). "Insulin levels were significantly higher in psyllium-fed than in placebo-fed mice, indicating that this fiber may delay the progression of diabetes in the animal model." (PMID 23762869, 2013). "I said..so troublesome, very inconvenient” (2.5 years of insulin use/ 6 years of having diabetes)." (PMID 24164794, 2013). "Furthermore, studies have shown that β-cell-specific upregulation of IRS-2 promotes β-cell growth, survival, and insulin secretion, and therefore prevents diabetes." (PMID 23874448, 2013). "Insulin resistance may be manifested only by mild glucose intolerance for many years prior to the onset of frank diabetes, as the pancreas is able to generate sufficient levels of insulin to maintain glucose levels beneath the diabetic threshold." (PMID 23527159, 2013). "Our study demonstrates that H2 exerts metabolic effects similar to those of insulin and may be a novel therapeutic alternative to insulin in type 1 diabetes mellitus that can be administered orally." (PMID 23326534, 2013). "Diabetics with a diabetic history of more than one year and stabilized with antidiabetic medicines such as insulin, metformin, glibenclamide, and gliclazide and diabetics with controlled diabetes as revealed by HbA1c in the range 6.2-7% were taken for the study purpose." (PMID 24274772, 2013). "Diabetes treatments can be divided into those that increase endogenous insulin secretion, those that decrease insulin resistance, those that decrease glucose uptake from the intestine, and simple administration of exogenous insulin." (PMID 23983688, 2013). "Moreover, most patients with diabetes in our survey received sliding-scale insulin regimen alone, even though it has been shown that sliding-scale insulin by itself is associated with poor inpatient glycemic control and even deleterious effects." (PMID 24499564, 2013). "Most patients with type 2 diabetes will eventually need insulin to achieve diabetes control." (PMID 23829275, 2013). "Generally, the SVGD (+) patients were significantly younger, more often were active smokers, and manifested the higher prevalence of renal failure (defined as glomerular filtration rate (GFR) below 50 mL/min/1.73 m2) and diabetes mellitus treated with insulin than the SVGD (−) patients." (PMID 24151618, 2013). "Exposure of insulin-secreting cells to proinflammatory cytokines, fatty acids or oxidized low-density lipoproteins, mimicking physiopathological conditions that favor the development of diabetes, resulted in a decrease in Rab37 expression." (PMID 23826383, 2013). "The aim of this study is to evaluate whether an intervention with GSD-Y in groups of adolescents starting on insulin pumps and their parents leads to fewer diabetes-related family conflicts, increased perceived health and QoL and improved metabolic control." (PMID 24354899, 2013). "Insulin glycemic control in diabetes may modulate brain mitoKATP channel, thus reducing the brain injury and restoring neuroprotection elicited by sevoflurane post-conditioning." (PMID 23991188, 2013). "That’s why I took it” (3 years of insulin use/ 12 years of having diabetes)." (PMID 24164794, 2013). "The growing worldwide frequency of diabetes will probably increase as a result of the insulin or insulin related products therapy, and thus this disease may contribute to the development of additional cases of CRC." (PMID 24175949, 2013). "As a group of metabolic diseases characterized with high blood sugar, most diabetes is caused by either a lack of insulin for type 1 diabetes (T1D) or a blockage in the insulin signaling pathway for type 2 diabetes (T2D)." (PMID 23922971, 2013). "Recent work by the Exeter group has shown 2-h urine C-peptide:creatinine ratio is highly correlated with serum C-peptide measurements in the mixed-meal tolerance test in insulin-treated diabetes (r = 0.82 to r = 0.97) and with meal stimulated C-peptide in non-insulin-treated diabetes." (PMID 23413806, 2013).
diabetes (continued). "Insulin analogs, which are now widely used in diabetes therapy, may elicit biased insulin effects at cellular levels." (PMID 24115945, 2013). "Nitric oxide reduction could lower insulin-stimulated glucose intake in skeletal muscle, which contributes to insulin resistance and thus diabetes." (PMID 23437258, 2013). "Indeed, after inducing diabetes with a streptozotocin injection, diabetic male Wistar rats had rising insulin levels in the tear film after glucose stimulation." (PMID 23805032, 2013). "Living a life with diabetes depends on the individual injecting insulin several times daily or making regular adjustments to the continuous rate of insulin infusion through a pump-delivery system, monitoring blood glucose levels, and attending closely to diet and exercise." (PMID 25530652, 2013). "In contrast, in those children who had at least two diabetes-associated autoantibodies at this age, the spontaneous decline in antibovine insulin antibody titer did not occur, instead the titers further increased." (PMID 24285974, 2013). "Insulin glycemic control can prevents alteration in brain mitoKATP channel, consequently limit ischemic brain injury and restore neuroprotective effects of anesthetic post-conditioning in diabetes." (PMID 23991188, 2013). "In obese subjects and patients with diabetes, the insulin EC50 (i.e., the insulin concentration that produces 50% of the maximal effect) is increased two- to threefold, indicating that adipose tissue lipolysis is at least as resistant to the action of insulin as muscle and liver." (PMID 24192824, 2013). "A previous study concerning insulin-dependent people with diabetes in Finland reported that the relative mortality, compared with the general population, was more strongly influenced by duration of diabetes than by age." (PMID 23837500, 2013). "It is embarrassing” (2 years of insulin use/ 5 years of having diabetes)." (PMID 24164794, 2013). "In particular, diabetes mellitus (DM), the most common form of metabolic dysfunction and characterized by absolutely or relatively insufficient in insulin secretion or insulin action, currently affects more than 346 million people worldwide, with almost 3.4 million mortalities." (PMID 23874589, 2013). "Since dietary fatty acids (FAs) play a key role in the cell membrane and insulin sensitivity, some fatty acids may induce development of insulin resistance and consequently affect diabetes metabolic control." (PMID 23767760, 2013). "These canonical and non-canonical pathways are linked to diabetes onset, insulin signaling and production of adhesion molecules/nitric oxide." (PMID 23755276, 2013). "Impaired fuel metabolism in diabetes may lead to chronic accumulation of lipid oxidative metabolites within blood or tissues, which played a key role in insulin resistance and insulin secretion." (PMID 24391760, 2013). "Moreover, it has been demonstrated that glycation of insulin occurs during diabetes, and that glycated insulin represents a significant proportion of total circulating insulin in type 2 diabetes." (PMID 23365488, 2013). "Novel findings show that islet-like insulin-producing cells can be converted from iPSs, demonstrating the possibility of using patient-specific iPSs as a source of transplantable beta cells for cell-replacement therapies in diabetes." (PMID 22611393, 2012). "For the individual in 2003 managing diabetes with insulin cost US$ 273.6 or 75% of per capita GDP." (PMID 23171496, 2012). "Furthermore, our experimental design resulted in differences in both serum glucose and insulin between the two groups of patients with diabetes, complicating the interpretation of the study." (PMID 23051145, 2012). "The molecular mechanisms by which insulin accelerates wound healing in diabetes seem to be many." (PMID 22662132, 2012).
diabetes (continued). "Therefore, although leptin signaling is highly crucial for understanding the etiology of the diabetes, genetic elements that place demand on insulin action in response to obese states should be a focus of research using diabetes animal models." (PMID 23304119, 2012). "Diabetes-related emotional distress ranges from limited psychological problems to constant diabetes-related self-care behaviors such as regular blood sugar control, medications administration, insulin injection, and adherence to treatment regime." (PMID 23497508, 2012). "Impaired insulin signaling and β-cell function is critical to obesity induced diabetes." (PMID 23028558, 2012). "When the patient returns to the ward from theatre, it is important that there are clear written instructions for ward staff to manage the patient’s diabetes, including any plan for stopping intravenous insulin infusions and restarting the patient’s usual diabetes medication." (PMID 22943220, 2012). "Our results suggest that the vasodilation effect of insulin may play a significant role in the regulation of microvascular perfusion in patients with diabetes." (PMID 22262970, 2012). "The development of diabetes was monitored by an intraperitoneal glucose-tolerance test and plasma insulin concentration while periodontitis was assessed by identification of pathogens, quantification of periodontal soft tissue inflammation and alveolar bone loss." (PMID 23133617, 2012). ""I can't think why I went to the diabetes educator, but my readings were up and she suggested I see my GP and that I might need to go on insulin." (PMID 22413897, 2012). "We reasoned that the genes that modulate insulin production might be new targets for diabetes therapeutics." (PMID 22253604, 2012). "The fact that drastic lifestyle modifications, such as an altered diet and increased physical activity, have a profound influence on insulin resistance and the onset of diabetic complications clearly demonstrates the crucial role of skeletal muscle metabolism in diabetes mellitus." (PMID 22523676, 2012). "Furthermore, inhibition of beta-cell adaptation and insulin production by rapamycin was considered as the main mechanism of rapamycin-induced diabetes in mice." (PMID 22683661, 2012). "The observations related to blood parameters in severe diabetes suggest that chicory may be also capable to act through insulin-independent mechanisms." (PMID 23352214, 2012). "A previous study by our group in individuals with insulin resistance (pre-diabetes) demonstrated that consumption of 40 g/day type 2 RS derived from high amylose maize (HAM-RS2) for 12 weeks increased tissue insulin sensitivity by 19%, compared with an energy and carbohydrate-matched placebo." (PMID 22815837, 2012). "Surrogate markers of peripheral insulin activity, such as homeostasis model assessment and whole-body insulin sensitivity indexes, could also be useful for the early identification of patients with insulin resistance before the development of overt diabetes." (PMID 23316348, 2012). "Diabetes and tuberculosis should be treated aggressively with insulin." (PMID 23497638, 2012). "We too could show that this test for monitoring blood glucose, C-peptide and insulin levels can reliably identify diabetes in GMP." (PMID 22390349, 2012). "IGF-I’s action on insulin suppression via somatostatine has been tried in diabetes." (PMID 23148873, 2012). "Two major hurdles need to be surmounted for cell therapy for diabetes: (i) allo-immune rejection of grafted pancreatic islets, or stem/precursor cell-derived insulin-secreting cells; and (ii) continuing auto-immunity against the diabetogenic endogenous target antigen." (PMID 23227162, 2012). "Though we could not, in our studies, directly attribute the low expression of insulin genes to DPP4, the association of very high DPP4 with diabetes is a confirmed phenomenon." (PMID 22291902, 2012). "Diabetes mellitus was noted at the age of 33, and insulin therapy was initiated." (PMID 22567382, 2012).
diabetes (continued). "These patients, compared with those having an HbA1c level of <7.0%, appeared to have less education, younger age at diagnosis of diabetes, longer duration of diabetes, lower prevalence of hypertension and were more likely to use oral hypoglycemia drug and insulin." (PMID 23077514, 2012). "The inverse testosterone-diabetes relation in men remained after adjusting for BMI and fasting insulin in our study, suggesting that there may be an alternative pathway relating testosterone and diabetes." (PMID 23066943, 2012). "She had a longstanding history of type 2 diabetes mellitus treated with subcutaneous insulin." (PMID 22937294, 2012). "This drug induces diabetes by intracellular generation of ROS formed in a cyclic reaction involving alloxan and its reduced product called dialuric acid, with subsequent inhibition of insulin synthesis and secretion." (PMID 22645603, 2012). "It seems that many genes, interacting with the receptor, are indeed regulated in the arterial wall in diabetes, which is in accordance with the idea that dysfunctional effects of insulin may play a role in diabetic arterial disease." (PMID 22340758, 2012). "Proposed mechanisms for such a possible link between diabetes and thyroid cancer include elevated levels of thyroid-stimulating hormone, insulin, glucose and triglycerides, insulin resistance, obesity, vitamin D deficiency, and antidiabetic medications such as insulin or sulfonylureas." (PMID 22778714, 2012). "Moreover, the plasma glucose levels in rats with diabetes for 8 weeks were markedly reversed by treatment with either insulin or phlorizin for 4 days, as compared to untreated diabetic rats." (PMID 22257425, 2012). "Although it is unknown whether low serum amylase fully reflects PEI, it is possible that low serum amylase may be partially related with pathogenesis of PEI considering that insulin action is impaired in both type of diabetes." (PMID 22748134, 2012). "Treatment with AS101 before manifestation of hyperglycemia, resulted in increased insulin sensitivity, and decreased blood glucose levels, and prevented symptoms of diabetes including defective glucose clearance, fatty liver, and abnormal distribution of insulin-producing beta cells in the pancreas." (PMID 22761194, 2012). "Diabetes may result in decreased insulin levels in the hippocampus because of impaired insulin transportation to the hippocampus, and may therefore affect memory." (PMID 22800811, 2012). "In contrast with neurosensory disorders, anemia and diabetes improve with pharmacological doses of oral thiamine and may lead to insulin discontinuation." (PMID 22284844, 2012). "The relationship between diabetes and health status is complex, and it can be difficult to speculate which aspect of the insulin therapy may explain the observed result." (PMID 22150786, 2012). "Insulin is involved in multiple regulatory mechanisms, including body weight and food intake, and plays a critical role in metabolic disorders such as obesity and diabetes." (PMID 23251461, 2012). "Here, we analyzed the differences in insulin signalling and inflammatory pathways in the blood and visceral adipose tissue of equally obese people that just differ in their insulin resistance and diabetes state." (PMID 23110196, 2012). "Furthermore, there is an overwhelming number of different oral hypoglycemic agents and insulin for the treatment of diabetes." (PMID 22247979, 2012). "The results of the present study suggest that chicory may exert both short- and long-term effects on diabetes, the former being under the influence of insulin and through its insulin-sensitizing action." (PMID 23352214, 2012). "In contrast to the protective effect of metformin, exogenous insulin use could promote tumor growth resulting in more advanced stage cancer at diagnosis among those with previously diagnosed and treated diabetes." (PMID 23259613, 2012).
diabetes (continued). "A significant obstacle to intensive insulin management is fear of hypoglycaemia, which has detrimental effects on people’s willingness to effectively manage their diabetes, particularly in terms of appropriate insulin dosing (e.g., under-dosing of insulin to avoid hypoglycaemia)." (PMID 23062116, 2012). "Our data revealed that 11 weeks of a high-carbohydrate diet, or the administration of a single intraperitoneal injection of streptozotocin, resulted in a modest model of obesity or diabetes, as demonstrated by changes in body weight, blood glucose levels, plasma insulin, and plasma leptin levels." (PMID 23125848, 2012). "Apparently, both endothelium-dependent and -independent coronary vasodilator function abnormalities are related to the chronic hyperglycemia and not to the type of diabetes (insulin-deficient versus insulin-resistant)." (PMID 24278760, 2012). "Internet survey of 1250 physicians (600 specialists, 650 primary care physicians) who treat patients with diabetes and telephone survey of 1530 insulin-treated patients (180 with Type 1 diabetes, 1350 with Type 2 diabetes) in China, France, Japan, Germany, Spain, Turkey, the UK or the USA." (PMID 22313123, 2012). "These are the insulin-producing cells of the body, so once their numbers have dwindled below a threshold level, the body loses the ability to regulate blood glucose levels, and diabetes ensues." (PMID 23251813, 2012). "Also the intake of insulin medication during pregnancy was a relatively strong predictor of diabetes (HRINS_PREGN = 11.01 (1.47–82.68), P<0.02)." (PMID 23185618, 2012). "Within this sample of out-patients with diabetes, we found that female gender, older age, low income, treatment with combine insulin and oral medications, poorly controlled T2DM, and those with coexisting complications of diabetes were independent risk factors for depression symptoms." (PMID 22909306, 2012). "In this case, diabetes appears earlier in males than in females, with low plasma insulin concentration and increased proinsulin/insulin ratio, which in the long-term may lead to insulin deficiency." (PMID 22284844, 2012). "For a therapeutic and sustained amelioration of the autoimmune state, including a permanent elimination of insulin-autoreactive T cells in diabetes, potentially leading to a sustained return of C-peptide secretion, more frequent or higher dosing of BCG will likely be required." (PMID 22905105, 2012). "In view of the benefits of a multidisciplinary team approach, Malaysia’s healthcare system should empower the allied health workers, such as the medical assistants, by continuously training and enhancing their knowledge and skills on diabetes care, including insulin initiation." (PMID 22545648, 2012). "Type 2 diabetes mellitus is generally managed through a stepwise program of intensive therapy that consists of lifestyle and sequential addition of oral antihyperglycemic agents (OHAs) and insulin as necessary." (PMID 22609782, 2012). "Diabetes mellitus is a metabolic disorder of multiple aetiologies that is characterized by chronic hyperglycaemia with disturbed carbohydrate, fat and protein metabolism resulting from defects in insulin secretion, insulin actions or both." (PMID 23039079, 2012). "Furthermore, he was receiving care in the endocrinology department and was using NPH (neutral protamine Hagedorn) insulin, but with poor diabetes control." (PMID 22344360, 2012). "On the other hand, diabetes and impaired glucose tolerance are characterized by a progressive loss of β-cell glucose sensitivity, independent of insulin resistance." (PMID 23133447, 2012). "However, individuals with a previous history of IAH and SH and longer duration of diabetes have typically been excluded from randomized clinical trials investigating insulin analogues." (PMID 23237320, 2012).